BECN1 (beclin 1)
Diseases named in the same sentence as BECN1 in open-access papers (continued):
Sharing a sentence is not in itself a finding about the gene and the disease.
tumor (continued). "Monoallelic deletion of the autophagy-related gene, beclin 1, was known to increase the incidence of spontaneous tumors in lung, liver and lymphoid tissue, suggestive of an anti-tumor effect of autophagy." (PMID 26984766, 2016). "TGF-β1 pro-treatment in Star-treated NIH3T3 fibroblasts significantly enhanced the expression of BNIP3, Beclin 1 and LC3β-II/I conversion in the mixed xenograft tumor, while 3-MA suppressed the effects of TGF-β1." (PMID 26716641, 2016). "High Beclin-1/high SIRT1 expression was also associated with tumor size (p = 0.002), histological grade (p = 0.001), LN metastasis (p < 0.001), tumor invasion (p = 0.026), TNM stage (p < 0.001), and VCE (p = 0.030)." (PMID 28070138, 2016). "Herein, we analyzed the epigenetic mechanism that regulates the transcription of Beclin-1, a tumor suppressor and an autophagy-related gene (ATG)." (PMID 27174920, 2016). "Bcl-xl, also called Bcl-2L, is known to function through inhibition of the autophagy effector and tumor suppressor Beclin-1." (PMID 27829861, 2016). "Our data showed that high RNF216 level negatively correlated with BECN1 expression, consistent with the role of BECN1 as a tumor suppressor." (PMID 27203674, 2016). "Tumor suppressive roles for autophagy were demonstrated in mice with Becn1/Beclin-1 heterozygosity, systemic mosaic Atg5 deletion or liver-specific deletion of Atg7." (PMID 26956429, 2016). "We suggest that when tumor cells are starved from nutrients and oxygen (supplied by blood flow), Beclin-1 mediated-autophagy stops cancer cells from dying by inhibiting apoptosis." (PMID 27043621, 2016). "We classified Beclin-1 cytoplasmic staining of tumours as positive (+) if one or more cores exhibited a moderate or strong cytoplasmic Beclin-1 immunostaining regardless of amount of stained tumour cells or negative." (PMID 27444698, 2016). "p62 and Beclin-1 immunohistochemistry of the tumour tissue revealed varying nuclear and cytoplasmic immunostaining." (PMID 27444698, 2016). "The expression of LC3β and beclin-1 in tumor cells was predominantly localized to the cytoplasm, in contrast to their absence in normal crypts." (PMID 26965179, 2016). "In tumour xenografts, the expression of 2KR mutant Beclin 1 (substitution of K430 and K437 to arginines) leads to enhanced autophagosome maturation and tumour growth suppression." (PMID 26008601, 2015). "Although tumor cells harbored high levels of Mcl-1 and low levels of Beclin 1 – a relationship inversely found in normal cells – a more detailed understanding of how Usp9X regulates both apoptosis and autophagy is necessary." (PMID 26008975, 2015). "Beclin 1 overexpression, as well as Beclin 2 overexpression and depletion, contributed to tumor growth." (PMID 26506105, 2015). "Beclin 1 WT MCF7 xenografts displayed strong Ki-67 staining homogenously in nearly all tumour cells, whereas the majority of tumour cells in Beclin 1–2KR xenografts displayed weak Ki-67 staining." (PMID 26008601, 2015). "In fact, the identifying Beclin-1 as a tumor suppressor gene in human cancer provided early evidence for the tumor suppressive role of autophagy." (PMID 26561802, 2015). "We compared Beclin 1 and Beclin 2 expressions with age, sex, tumor size, lymph node status, metastasis, stage, grade, lymphovascular invasion, and necrosis." (PMID 26506105, 2015). "Taken together, these results demonstrate that acetylation of Beclin 1 promotes cell proliferation and tumour growth." (PMID 26008601, 2015).
tumor (continued). "Recently, BECN1 has been reported to be positively correlated with tumor differentiation in several cancers, and can be used as an independent biomarker for predicting overall survival and progression-free survival in gastric and liver cancer patients." (PMID 26497999, 2015). "The impacts of Beclin 1 and Beclin 2 on autophagy and tumor growth were evaluated by conversion of LC3-I to LC3-II and by clonogenic assays, respectively." (PMID 26506105, 2015). "One of the earliest and representative results supporting the tumor suppressive role of autophagy was related to Beclin-1-knockout mice." (PMID 26561802, 2015). "Expression of beclin-1 in the tumor stroma also has an important role in the development of various cancers." (PMID 25955408, 2015). "To further confirm the importance of autophagy inhibition in sensitization to DDP treatment, we inhibited autophagy in FaDu cells with shRNA to Beclin-1 and assessed the effect on xenograft tumor growth." (PMID 25923669, 2015). "DNA sequencing of human breast and ovarian cancer has shown that Beclin 1 is often lost leading to neoplasm." (PMID 25730388, 2015). "Numerous studies confirm that Beclin-1 is a tumor suppressor gene that shows decreased expression in various tumor tissues." (PMID 26494988, 2015). "Beclin 1, also considered as a haploinsufficient tumor-suppressor gene, that was often monoallelically deleted in many types of cancer, signifying its vital role in autophagic cell death during cancer therapy." (PMID 26436418, 2015). "Beclin-1 has gained notoriety due to its role in mediating autophagy and its role as a tumor suppressor in genetically modified mice." (PMID 26239434, 2015). "In this study, we identify an acetylation-dependent regulatory mechanism governing Beclin 1 function in autophagy for the first time, and Beclin 1 acetylation can inhibit autophagosome maturation and promote tumour growth." (PMID 26008601, 2015). "MCF7 cells with stable expression of vector control, wild-type or 2KR-mutant Beclin 1 were injected into nude mice, and tumour cell growth was monitored over a period of 38 days." (PMID 26008601, 2015). "On the one hand, it was demonstrated that various ATGs suppress tumor growth and that accordingly different autophagy-compromised mice are tumor-prone, e.g., Becn1+/− mice." (PMID 26390974, 2015). "Among the autophagy-related genes, beclin 1 established the first connection between autophagy and cancer, and regarded as a haploinsufficient tumor suppressor gene." (PMID 26506105, 2015). "Tumor samples from subject who died had lower Beclin 1 and LC3B expressions within both CT and NM region compare with survival patients." (PMID 25762626, 2015). "Another recent report links Usp9X to Beclin-1, a gene that is known as a tumor suppressor and a modulator of autophagy." (PMID 26008975, 2015). "MCF7 cells were transduced with retroviruses that express Flag epitope-tagged wild-type Beclin 1 or Beclin 1 S90A; injected into nu/nu mice implanted with slow release estrogen tablets; and monitored for their rate of tumor growth." (PMID 25693418, 2015). "Abnormal expression of Beclin 1 in tumor tissue is correlated with poor prognosis and aggressive tumor phenotypes." (PMID 25617802, 2015). "Our research further clarifies the mechanism of Beclin 1-regulating autophagosome maturation, offering new targets and ideas for tumour therapy." (PMID 26008601, 2015). "CK1γ2-mediated Beclin 1 phosphorylation promotes the subsequent acetylation of Beclin 1 by p300, and acetylation of Beclin 1 promotes cell proliferation and tumour growth." (PMID 26008601, 2015). "Other groups have reported novel NF-κB p65 consensus sites in the beclin 1 promoter and demonstrated that NF-κB p65 positively modulated canonical autophagy in various human tumor cell lines." (PMID 25895124, 2015). "This discordance in both knockout phenotype as well as tumor spectrum suggests additional functions of Beclin-1 separate from its role in autophagy." (PMID 26239434, 2015).
tumor (continued). "It demonstrated that the tumours derived from Beclin 1 WT-expressing cells were more proliferative than those derived from cells expressing Beclin 1–2KR." (PMID 26008601, 2015). "Immunoblotting of the 4-MU treated and untreated cells also revealed a substantial upregulation of the other autophagy marker and tumor suppressor, Beclin 1 upon 4-MU treatment." (PMID 25061661, 2014). "BECLIN 1 immunoreactivity in tumour cells presented as a faintly detectable staining diffused in the cytoplasm or as discrete stained puncta (referred to as granular-type) clearly evident in the vicinity of the nucleus." (PMID 25136588, 2014). "Using univariate Cox regression analysis, the parameters such as tumor size (>5 cm), Edmondson grades (III + IV), TNM stage (III + IV), vascular invasion and capsular infiltration and Beclin-1 expression (− and +) were significantly associated with poor OS." (PMID 24885292, 2014). "Bcl-2 family of proteins has also been implicated in autophagic cell death, wherein, Bcl-2 can bind to Beclin-1 (a haploinsufficient tumor suppressor) and inhibit its activity." (PMID 25121098, 2014). "Beclin 1, an autophagic regulator, is essential for early embryonic development, and is a haploinsufficient tumor suppressor." (PMID 24967584, 2014). "In particular, of the 41 patients bearing a tumour highly expressing BECLIN 1, 34 (~83%) were still alive at the end-point of the study and only 7 (17%) died during the observation period." (PMID 25136588, 2014). "It is already reported that induction of autophagy by paclitaxel treatment plays a major role in the development of paclitaxel resistance in tumor cells with upregulation of BECN1." (PMID 24755562, 2014). "The first data pointing towards the possible tumor suppressor role of autophagy were obtained in studies of Beclin-1." (PMID 25328887, 2014). "Treatment of tumor cells with the mimic of miR-30a decreased the expression of Beclin-1 mRNA and protein, whereas administration of the miR-30a antagomir increased Beclin-1 levels." (PMID 25317422, 2014). "Tumors forming in BECN1+/− mice express wild-type BECN1 mRNA and protein, indicating that Beclin-1 is a haploinsufficient tumor suppressor." (PMID 25317422, 2014). "Based on the proportion of BECLIN 1-positive cells within the tumour tissue, the samples were initially stratified into four ranges of positivity: <10%; 10–20%; 20–40%; >40%." (PMID 25136588, 2014). "Beclin 1 (the ortholog of yeast Atg6) was the first mammalian autophagy protein to be identified, and is a haplo-insufficient tumor suppressor gene." (PMID 24438216, 2014). "By contrast, a statistically significant correlation was found between the high expression of BECLIN 1 (i.e., tumours with ≥20% of positive cells) and patient's OS." (PMID 25136588, 2014). "In general, the clinically indolent type I tumours were more frequently expressing BECLIN 1 at high level." (PMID 25136588, 2014). "DEF was 4.5 for ATG5KD tumours and 3.7 for BECN-1KD tumours, revealing ATG5 or BECN-1 depletion sensitized A549 tumours to IR." (PMID 24037090, 2014). "Tumor size (>5 cm), Edmondson grades (III + IV), TNM stage (III + IV), vascular invasion, capsular infiltration and low expression of Beclin-1 (− and +) were significantly associated with poor OS." (PMID 24885292, 2014).
tumor (continued). "Consistent with Beclin 1 upregulation, immunocytochemical analysis of HepR21 cells after 4-MU treatment also led to elevated expression of the autophagic modulator and tumor suppressor PTEN." (PMID 25061661, 2014). "It was reported that Beclin 1 expression was inversely correlated with tumor differentiation, nodal and distant metastasis and tumor relapse." (PMID 24527069, 2014). "Alternatively, the expression of a tyrosine phosphomimetic mutant of Beclin-1 reduces autophagy and increases tumor growth." (PMID 25328887, 2014). "Some tumor suppressors induce autophagy, for example, Beclin 1, UVRAG, PTEN and Bcl-2, while some oncogenic proteins like mTOR inhibit autophagy." (PMID 25121098, 2014). "Together this showed that Beclin-1 together with tumor size, tumor differentiation, and TNM stages were strongly associated with OS." (PMID 24885292, 2014). "Beclin 1, one essential component of autophagy, has been identified as a haplo-insufficient tumor-suppressor gene." (PMID 23573264, 2013). "As the first identified mammalian autophagy effector, Beclin 1, also known as Atg6, played an essential role both in tumor formation and progression." (PMID 24303007, 2013). "First of all, expression of Beclin 1 stabilizes chromosome structure thereby prohibiting the process of carcinogenesis and tumor progression." (PMID 24260370, 2013). "The leucine-rich nuclear export signal of Beclin-1 is essential for autophagic growth control and tumor suppression." (PMID 23578251, 2013). "We found that, compared with normal adjacent tissues, Beclin 1 was lowly expressed in tumor zone both in ICC and ECC." (PMID 24303007, 2013). "Our results suggest that Beclin-1 plays a significant role in tumor progression and can be a potential therapeutic target for malignant CMTs in the future." (PMID 23578251, 2013). "Multivariate survival analysis using the Cox proportional hazard regression method revealed that tumor size, tubular formation, and Beclin-1 cytoplasmic expression were independent prognostic factors for malignant CMTs." (PMID 23578251, 2013). "Our data showed that Beclin 1 was significantly lower in NSCLC tissues compared with the adjacent normal tissues, negatively associating with tumor recurrence rate (65.8% VS 32.3%; p < 0.001)." (PMID 24260370, 2013). "Combining Beclin 1 level with tumor location led to a more accurate prognosis definition for ICC and ECC." (PMID 24303007, 2013). "Combined Beclin 1 expression with tumor location would lead to a more accurate prognosis prediction for the subtypes of ICC and ECC." (PMID 24303007, 2013). "Accordingly, as the central player of autophagy, Beclin 1 had a double-edged function in regulating tumorigenesis and other malignant phenotypes, and in predicting the prognosis for different tumor types." (PMID 24303007, 2013). "Regardless, however, the fact that Beclin-1 is an established tumor suppressor suggests that its inhibition by tumor virus proteins such as vBcl-2 importantly contributes to host cell transformation." (PMID 24710474, 2012). "ERK induction of autophagy occurs in response to anti-tumor/cytotoxic stimuli through modulating Beclin-1 expression." (PMID 24710529, 2012). "Despite that treatment with TMZ-Se activated autophagy in tumor cells, we unexpectedly found that the expression of Beclin 1, a key regulator of autophagy, was down-regulated in tumor cells treated with this compound, as examined by Western blot." (PMID 22496897, 2012).
tumor (continued). "The mammalian ortholog of the essential PtdIns-3KC3 component Vps30/Atg6, Beclin 1, has gained a special interest in autophagy research, because it was the first autophagy protein shown to be a haploinsufficient tumor suppressor." (PMID 24710477, 2012). "Vps34 activation is dependent on the formation of a multiprotein complex involving Beclin-1, UVRAG (UV irradiation resistance-associated tumor suppressor gene), a myristylated kinase p150 and Atg14L." (PMID 24710529, 2012). "It has been generally believed that Beclin 1 functions as a haploinsufficient tumor suppressor via autophagy activation." (PMID 23270461, 2012). "The tumor-suppressive role of autophagy was first shown in mice heterozygous for the Beclin 1 autophagy protein." (PMID 22496691, 2012). "It was previously reported that Beclin 1 participates in inhibition of apoptosis, and that silencing of Beclin 1 expression augments the mitochondrial permeabilization and apoptosis induced by Fas stimulation or doxorubicin treatment in tumor cells." (PMID 22496897, 2012). "It was found that Beclin-1 in all four tumor tissue specimens had a significantly higher expression at both mRNA and protein levels than those in the normal tissue adjacent to tumors from the same patients." (PMID 23029344, 2012). "Beclin-1 was the first mammalian Atg protein to be identified and the first Atg protein that was established as a tumor suppressor." (PMID 24710474, 2012). "Beclin 1, the mammalian homologue of the yeast Atg6 was initially identified as a Bcl2-interacting tumor suppressor." (PMID 23270461, 2012). "Numerous studies suggest that Beclin 1, a rate-limiting autophagy protein, is a haploinsufficient tumor suppressor gene." (PMID 21611191, 2011). "The tumor suppressor activity of Beclin 1 has been attributed to its interactions with proteins that regulate cell death and autophagy." (PMID 21455500, 2011). "Our present data suggest an additional mechanism for the tumor suppressor functions of Beclin 1, namely its ability to bind FYVE-CENT and participate in the regulation of cytokinesis." (PMID 21455500, 2011). "The tumor suppressor activity of Beclin 1 (BECN1), a subunit of class III phosphatidylinositol 3-kinase complex, has been attributed to its regulation of apoptosis and autophagy." (PMID 21455500, 2011). "We therefore examined the effect of Beclin 1+/− on tumor development in Lck-Casp9DN, Lck-Bax1, and Lck-Bax38/1 transgenic mice." (PMID 21611191, 2011). "BECN1 is a haplosufficient tumour suppressor gene and Beclin+/− mice suffer from a high incidence of spontaneous tumours." (PMID 21887344, 2011). "Since Beclin 1 is a well-known tumor suppressor, we therefore wanted to test the cell biological consequence of such mutations in the context of FYVE-CENT interaction." (PMID 21455500, 2011). "Collectively, our findings reveal a novel regulatory role of the tumor suppressor Beclin 1 and its binding partner FYVE-CENT that has potential implications for carcinogenesis." (PMID 21455500, 2011). "Beclin 1 is an essential autophagy gene for early embryonic development and reported to be a haploinsufficient tumor suppresser gene based on genetic studies in human cancer samples as well as gene heterozygous deletion studies in mice." (PMID 21611191, 2011). "Further, we show that a tumor-associated mutation of FYVE-CENT abolishes its interaction with Beclin 1, prevents recruitment of Beclin 1 to the intercellular bridge, and is accompanied by cytokinesis arrest and multinuclear phenotype." (PMID 21455500, 2011). "Beclin 1 is a rate-limiting component of the autophagy pathway and has been shown to be a haploinsufficient tumor suppressor." (PMID 21611191, 2011). "Because aberrant cytosine methylation within 5' end of tumor suppressor genes is commonly observed in cancer cells, beclin 1 was likely a candidate gene for epigenetic silencing." (PMID 20230646, 2010).